PGR (progesterone receptor)
Diseases named in the same sentence as PGR in open-access papers (continued):
Sharing a sentence is not in itself a finding about the gene and the disease.
breast cancer (continued). "Human‐induced pluripotent stem cell‐derived cardiomyocytes (iCell) and an oestrogen and progesterone receptor‐positive human breast cancer cell MCF7 were used for investigating changes in cell death profiles in response to chemotherapeutic drugs." (PMID 34931757, 2022). "Based on the Ki-67 labeling index, which is used to detect cell proliferation and analyze the status of the estrogen (E) and progesterone receptor (PgR), breast cancer is divided into basal-like, luminal A, and luminal B subtypes." (PMID 36551512, 2022). "In breast cancer, RNF8 is associated with many key clinical parameters such as estrogen receptor status, IHC positive cells, and progesterone receptor." (PMID 35831895, 2022). "From a histopathological perspective, breast cancer comprises three main subtypes: hormone receptor positive (estrogen receptor+ [ER+], progesterone receptor+ [PR+]), HER2-positive (HER2+), and triple negative breast cancer (TNBC)." (PMID 36551663, 2022). "In 2012, a 62-year-old white native Finnish woman was operated on for an estrogen and progesterone receptor-positive breast cancer." (PMID 36522673, 2022). "Metabolic reprogramming remains largely understudied in relation to hormones in estrogen receptor (ER) and progesterone receptor (PR) positive breast cancer." (PMID 35406548, 2022). "Breast cancer has several subtypes based on estrogen receptor, progesterone receptor, and human epidermal growth factor receptor 2 (ER/PR/HER2) status." (PMID 35299966, 2022). "Nearly 70% of breast cancers express estrogen receptor (ER), progesterone receptor (PR), or both and proliferate in the presence of estrogen." (PMID 35177031, 2022). "TNBC encompasses a subtype of breast cancers that lack the expression of the estrogen receptor (ER), the progesterone receptor (PR), and the human epidermal growth factor receptor 2 (HER2)." (PMID 36613808, 2022). "Breast cancer is commonly classified into three subtypes based on the expression status of estrogen receptor (ER), progesterone receptor (PR), and human epidermal growth factor receptor 2 (HER2)." (PMID 35572726, 2022). "The widely reported conflicting effects of progestin on breast cancer suggest that the progesterone receptor (PR) has dual functions depending on the cellular context." (PMID 36009407, 2022). "Breast cancer is subdivided into three main molecular subtypes according to the expression pattern of estrogen receptor (ER), progesterone receptor (PR), human epidermal growth factor receptor 2 (HER2), or none of them (triple negative breast cancer, TNBC)." (PMID 36544904, 2022). "The progesterone receptor (PgR) is one of the most important prognostic and predictive immunohistochemical markers in breast cancer." (PMID 35563727, 2022). "The three most common molecular subtypes of breast cancers based on the coding genome are HR+ malignancies (estrogen receptor-positive (ER+) and progesterone receptor positive (PR+) breast cancers), HER2+, and triple-negative breast cancer (TNBC) malignancies." (PMID 36358806, 2022). "Breast cancers are diverse and often identified by molecular subtype via immunohistochemical (IHC) expression of prognostic markers: estrogen receptor (ER), progesterone receptor (PR), and the human epidermal growth factor receptor 2 (HER2)." (PMID 35371975, 2022). "Accumulating preclinical evidence has uncovered the indispensable role of steroid hormone and their receptors, namely, estrogen receptor (ER) and progesterone receptor (PR), in the development of bone metastases in breast cancer." (PMID 36091103, 2022). "Characterization of breast cancer is often leveraged to classify patients into disease pathways based on surface receptor expression of Estrogen receptor (ER), Progesterone receptor (PR), and Human epidermal growth factor receptor 2 (HER2)." (PMID 36630696, 2022). "The role of estrogen and progesterone receptor in the development of breast cancer has been recognized worldwide." (PMID 35800434, 2022).
breast cancer (continued). "Breast cancer is a heterogeneous disease, classified largely by the expression of the estrogen receptor (ER), progesterone receptor (PR), and by amplification of the human epidermal growth factor receptor 2 (HER2)." (PMID 35618789, 2022). "Conversely, HMGB3 expression was negatively associated with the expression of estrogen receptor (ER) and progesterone receptor (PR) in breast cancer." (PMID 36620553, 2022). "Level of WWOX expression correlated both with estrogen and progesterone receptor status in a study, where 132 breast cancer cases were evaluated utilizing quantitative real-time RT-PCR." (PMID 35290621, 2022). "Breast cancer often presents the expression of three markers that allow the classification of these tumors, which are the estrogen receptor (ER), progesterone receptor (PR), and amplification of HER-2/Neu." (PMID 36559104, 2022). "Triple-negative breast cancer (TNBC) is a breast cancer (BC) subtype that lacks expression of estrogen receptor (ER), progesterone receptor (PR), and HER2 and accounts for 15–20% of BC cases worldwide." (PMID 36362107, 2022). "There are four major subtypes of breast carcinoma based on estrogen receptor (ER), progesterone receptor (PR) and human epidermal growth factor receptor 2 (HER2) status." (PMID 36530981, 2022). "The role of progesterone receptor (PR) and its interplay with estrogen receptor (ER) in breast cancer is controversial." (PMID 35668111, 2022). "The estrogen receptor is expressed in 80% of breast cancer cases, the progesterone receptor in 60%, and GCDFP-15 in 70%." (PMID 34410532, 2021). "Pathological examination showed peritoneal dissemination of breast cancer, but the biological markers were different from the primary lesion: ER(−), PgR(−), and Her2:3 +." (PMID 33489710, 2021). "The majority had estrogen receptor (ER)-positive (77.6%) and progesterone receptor (PR)-positive breast cancer (67.2%), and only 34.3% of patients had positive HER2 receptors." (PMID 34660301, 2021). "The molecular subtypes of breast cancer are classified based on the status of estrogen receptor (ER), progesterone receptor (PR), and human epidermal growth factor receptor 2 (HER2)." (PMID 33986665, 2021). "Breast cancers expressing higher than 10% of ER and higher than 20% of PgR show an optimized tendency to be considered as typical HR-positive breast cancers." (PMID 34638491, 2021). "From a clinical perspective, breast cancers are classified based on the expression of oestrogen receptor (ER), progesterone receptor (PgR), and human epidermal growth factor receptor 2 (HER2)." (PMID 33673506, 2021). "Histological markers of breast cancer are expressions of the estrogen receptor (ER), the progesterone receptor (PR), and human epidermal growth factor receptor (HER)-2." (PMID 33461170, 2021). "Breast cancers that lack expression of the estrogen receptor (ER), progesterone receptor (PR), and human epidermal growth factor receptor 2 (HER2) are categorized as triple-negative breast cancers (TNBCs), which comprise 10%–20% of all breast cancers." (PMID 34448553, 2021). "ER and PgR are a few of the essential biomarkers related to the clinical patterns, treatment decision, and prognosis of breast cancer." (PMID 34638491, 2021). "SRC-3Δ3 was more potent than full-length SRC-3 in enhancing estrogen receptor (ER) and progesterone receptor (PR) signaling, and its overexpression was found in breast cancer specimens." (PMID 33946224, 2021). "Like dual inhibition of estrogen and mTOR or CDK4/6 in recurrent/metastatic ER-α/PgR-positive breast cancer, the possibility of dual inhibition of androgen and mTOR or CDK4/6 is now attracting interest in TNBC." (PMID 34070471, 2021). "Among a host of biomarkers important for the clinical management of breast cancer (BC), estrogen receptor (ER), progesterone receptor (PR), and HER2 are the most crucial." (PMID 35145903, 2021).
breast cancer (continued). "ILBCs are typically oestrogen receptor (ER) and progesterone receptor (PR) positive and human epidermal growth factor receptor 2 (HER2) negative and are strongly associated with hormonal risk factors for breast cancer." (PMID 33461604, 2021). "Oestrogen receptor (ER) or progesterone receptor (PgR)-positive breast cancer is recognised in approximately 70–80% of IBrC patients." (PMID 34070058, 2021). "Most breast cancer patients, however, are elderly, so their basal PgR levels should be low, reflecting low menopausal estrogen levels." (PMID 33531464, 2021). "Breast cancer management depends on biomarkers including estrogen receptor, progesterone receptor, and human epidermal growth factor receptor 2 (ER/PR/HER2)." (PMID 35602213, 2021). "This study reconfirmed that HR-positive breast cancer with low levels of both ER and PgR expression had clinicopathologic patterns similar to HR-negative breast cancer." (PMID 34638491, 2021). "Different special type breast cancers display varying proportions of expression of estrogen receptor (ER), progesterone receptor (PR), and HER2/neu." (PMID 33824803, 2021). "Breast cancer is classified into histological subtypes using hormone receptors namely oestrogen receptor (ER) and progesterone receptor (PR) as well as human epidermal growth factor receptor 2 (HER2)." (PMID 33854679, 2021). "Breast cancers are classified based on the status of the estrogen receptor (ER), progesterone receptor (PR), and human epidermal growth factor receptor (HER2)." (PMID 34830174, 2021). "Hormone receptors include the estrogen receptor alpha (ERα), the main driver of breast cancer cell proliferation, and the progesterone receptor (PR), a gene regulated by ER, both acting as hormone-dependent transcription factors." (PMID 34359587, 2021). "Accordingly, previous studies have demonstrated that drugs targeting ESR1, ESR2, and PGR are effective in the treatment of breast cancer and improve promote clinical outcomes." (PMID 34322374, 2021). "Women with oestrogen or progesterone receptor positive breast cancer typically receive endocrine therapies, either tamoxifen or aromatase inhibitors (AIs), to reduce cancer recurrence risk." (PMID 33177117, 2021). "Human epidermal growth factor receptor 2 (HER2) estrogen (ER) and progesterone (PgR) are three cell surface molecules typically used as therapeutic targets in current breast cancer treatment." (PMID 34830933, 2021). "Two thirds of patients are classified as hormone receptor positive, based on expression of estrogen receptor alpha (ERα), the main driver of breast cancer cell proliferation, and/or progesterone receptor, which is regulated by ERα." (PMID 34359587, 2021). "Triple-negative breast cancer (TNBC), responsible for around 15% of global breast cancer (BC) cases, is histopathologically featured by shortages of estrogen receptor (ER), progesterone receptor (PR) and human epidermal growth factor receptor (HER)-2." (PMID 34289449, 2021). "In 2012, Dutch researchers found that a combination of the levels of ER/PgR expression and 70-gene signature (MammaPrintTM, Agendia BV, Amsterdam; cleared by the FDA for risk assessment) was associated with 10-year breast cancer-specific patient survival." (PMID 34638491, 2021). "The ER and PgR status and their effects on breast cancer-specific survival (BCSS) and disease-free survival (DFS) over 5 and 10 years were evaluated." (PMID 33670083, 2021). "A majority of breast cancers are carcinomas, and their histological stratification is based primarily on the expression of estrogen receptor (ER), progesterone receptor (PR), and human epidermal growth factor receptor 2 (HER2)." (PMID 34449670, 2021). "Endocrine therapy targeting estrogen receptor or progesterone receptor is a well-tolerated treatment for some breast cancer patients." (PMID 35047402, 2021).
breast cancer (continued). "The intrinsic subtypes of breast cancer are classified based on the gene expression profiles of hormone receptors (HRs) (estrogen receptor, ER; progesterone receptor, PR) and human epidermal growth factor receptor 2 (HER2)." (PMID 33672831, 2021). "In this study, the HR group was newly organized by the combination of ER and PgR expression levels and was given significance as a prognostic factor for breast cancer." (PMID 34638491, 2021). "The predictive role of progesterone receptor (PgR) is controversial, with some studies showing a better response in ER+/PgR+ breast cancers than ER+/PgR- breast cancers." (PMID 33670042, 2021). "Accordingly, in principle, it also should be possible clinically to test the hormone sensitivity of breast cancer with FFNP-PET in order to monitor a decrease in PgR levels after a period of estrogen deprivation or ER blockade." (PMID 33531464, 2021). "Triple-negative breast cancer (TNBC), a heterogeneous breast cancer subtype, lacks endocrine estrogen receptor (ER) and progesterone receptor (PR) and human epidermal growth factor receptor 2 (HER2, encoded by ERBB2)." (PMID 34109118, 2021). "Lonaprisan (also called BAY 86-5044), which is a potent synthetic selective antagonist of the progesterone receptor and a potential treatment of breast cancer, has been shown to increase myelinated axon numbers and to improve poor motor phenotypes." (PMID 35076634, 2021). "Although the mechanism of the occurrence of breast cancers with ER/PgR +/− and −/+ is unclear, they occur at a rate of 2–5% of all the breast cancers." (PMID 34638491, 2021). "This subtype of breast cancer cells has expression of estrogen receptor (ER) and/or progesterone receptor (PR), thereby are sensitive to hormone therapy." (PMID 34689156, 2021). "Since the prognosis of breast cancer differs according to the molecular subtype, guidelines recommend core biopsy for immunohistochemical assessment of ER, PgR, and HER2 status to classify the molecular subtype of breast cancer during initial diagnosis." (PMID 33668933, 2021). "Four primary biomarkers are analyzed during the routine pathological work-up for breast cancer: estrogen receptor (ER), progesterone receptor (PR), human epidermal growth factor receptor 2 (HER2), and the proliferation-associated nuclear protein Ki67." (PMID 34869473, 2021). "The most useful tissue-based biomarkers in breast cancer include estrogen receptor (ER), progesterone receptor (PR), human epidermal growth factor receptor 2 (Her-2), and ki67 are used to detect prognosis and guiding systemic therapy." (PMID 34048188, 2021). "Several estrogen-inhibiting therapies are currently available for ER-α/PgR-positive breast cancer, which are largely divided into two categories: anti-ER therapy and therapy inhibiting estrogen production." (PMID 34070471, 2021). "Categorization of breast cancer based on its status of estrogen receptor (ER), progesterone receptor (PR), and HER2 has markedly improved the treatment of the luminal and HER2-specific subtypes." (PMID 35156101, 2021). "The vast majority (60–75%) of breast cancers are classified as estrogen-receptor positive (ER+) or progesterone receptor positive (PR+)." (PMID 34573015, 2021). "Different types of breast cancer are typically classified based upon expression of estrogen receptor, progesterone receptor, and epidermal growth factor receptor." (PMID 34439373, 2021). "The main molecular biomarkers currently used in the diagnosis and treatment of breast cancer include estrogen receptor (ER), progesterone receptor (PR), cell proliferation antigen Ki67, and human epidermal growth factor receptor 2 (HER-2)." (PMID 34621293, 2021). "Triple-negative breast cancer (TNBC) is a unique subtype of breast cancer in which the estrogen receptor (ER), progesterone receptor (PR), and human epidermal growth factor receptor 2 (HER-2) are not expressed." (PMID 33968977, 2021).
breast cancer (continued). "The molecular classification of breast cancer is performed using the tumor markers progesterone receptor, ER, and Her2/neu." (PMID 34845427, 2021). "Estrogen and progesterone receptor-positive breast cancer patients with elevated EP4 expression were more likely to be non-responsive to neoadjuvant endocrine therapy." (PMID 33668160, 2021). "Treatment of TNBC is extremely challenging compared to other breast cancers that express one or more receptors such as the progesterone receptor (PR), estrogen receptor (ER) and human epidermal growth factor receptor (HER2)." (PMID 34359773, 2021). "Treatment for breast cancers are guided by the identification of hormone receptors, Estrogen receptor (ER), Progesterone receptor (PR), and Human Epidermal Growth Factor Receptor 2 (HER2)." (PMID 34350123, 2021). "ER and PgR are expressed to varying degrees, which results in differences in the prognosis and/or responsiveness of breast cancer to endocrine treatment." (PMID 34638491, 2021). "The present study showed that targets of Chrysanthemum phytochemicals (luteolin, chlorogenic acid, rutin, quercetin, and apigenin) belong to estrogen receptors such as ESR1, ESR2, and PGR and are major therapeutic targets of breast cancer." (PMID 34083561, 2021). "Out of the 26 patients, 1 patient with estrogen receptor-positive (> 95%), progesterone receptor-positive (60%)/HER2 amplified breast cancer achieved a PR (ORR 4%)." (PMID 34169393, 2021). "A test for downward change in PgR levels to predict ET responsiveness would be more feasible in premenopausal breast cancer patients." (PMID 33531464, 2021). "Expanded cord blood-NK cells show cytotoxicity towards primary breast tumor cells derived from TNBC and estrogen receptor-positive/progesterone receptor-positive breast cancer." (PMID 34283088, 2021). "Gallen consensus released the following year, it was defined that the best cutoff for PgR positivity with characteristics of HR-positive breast cancer was at least 20%." (PMID 34638491, 2021). "Breast cancer treatment is based on the receptor status of the tumor, specifically estrogen receptor (ER), progesterone receptor (PR) and human epidermal growth factor receptor-2 (HER2), as well as proliferative markers such as Ki67." (PMID 34043703, 2021). "Breast cancer subtypes are typically classified based on immunohistochemistry according to the expression of estrogen receptor (ER), progesterone receptor (PR), and human epidermal growth factor receptor 2 (HER2)." (PMID 34464510, 2021). "Most breast cancers are estrogen receptor (ER) and progesterone receptor (PR) positive (70%), while some overexpress human epidermal receptor 2 (HER2)." (PMID 33758708, 2021). "In breast cancer cells, PgR is a transcriptional target of ER, and estrogen is well known to be an important stimulator of PgR synthesis." (PMID 33981288, 2021). "The classification of breast cancer based on the coding region identified potential genetic targets including the CCND1 gene, which is amplified in 30 to 58% of breast cancers; the estrogen receptor (ERα); and/or progesterone receptor (PR) and Her2." (PMID 33485378, 2021). "Triple-negative breast cancer (TNBC) is a breast cancer subtype that lacks an estrogen receptor (ER), a progesterone receptor (PR), and a human epidermal growth factor receptor 2 (HER2)." (PMID 34357122, 2021). "This is further compounded by the heterogeneity of breast cancer, which can be generalized by the presence of three receptors: estrogen receptor (ER)‐positive, progesterone receptor (PR)‐positive, and human epidermal growth factor receptor 2 (HER2)‐positive." (PMID 33532588, 2021). "Immunohistochemical studies have classified breast cancer into four broad subtypes: oestrogen receptor-positive (ER+), progesterone receptor-positive (PR+), human epidermal growth factor receptor 2-positive (HER2+) and triple negative." (PMID 33809117, 2021).